PTPN11 (protein tyrosine phosphatase non-receptor type 11)
Diseases named in the same sentence as PTPN11 in open-access papers (continued):
Sharing a sentence is not in itself a finding about the gene and the disease.
LEOPARD syndrome (continued). "Animal studies suggested that blocking the activation of the mammalian target of rapamycin (mTOR) pathway might be effective to treat cardiac hypertrophy in LEOPARD syndrome (LS) caused by PTPN11 mutations." (PMID 31722741, 2019). "Approximately 90% of LEOPARD syndromes are caused by missense mutations in the PTPN11 gene, which encodes the ubiquitously expressed tyrosine phosphatase protein SHP2, although hypertrophic cardiomyopathy remains the most common abnormality in patients affected by LEOPARD syndrome." (PMID 28573431, 2017). "Pathogenic variants in PTPN11 are the most common cause of Noonan and LEOPARD syndromes." (PMID 27562378, 2016). "Mutations in PTPN11 are associated with Noonan and LEOPARD syndrome." (PMID 24736444, 2014). "Individuals with LEOPARD syndrome may have distinct mutations in PTPN11 wich lead to a diminished catalytic activity of these SHP-2 mutants." (PMID 17222357, 2007). "Notably, two patients were found to have LEOPARD syndrome due to PTPN11 gene variants." (PMID 41516100, 2025). "LEOPARD syndrome (LS) is defined by Lentigines, Electrocardiographic abnormalities, Ocular hyperthelorism, Pulmonary valve stenosis, Abnormal genitals, Retarded growth and Deafness, and is caused by heterozygous mutations in the protein tyrosine phosphatase, non-receptor type 11 gene (PTPN11)." (PMID 25884655, 2015). "Noonan syndrome with multiple lentigines (NSML) is a rare autosomal dominant disorder, primarily caused by variants in the PTPN11 gene." (PMID 39898109, 2025). "Given its links to Noonan and LEOPARD syndromes, conditions punctuated by distinct skeletal perturbations, the spotlight on PTPN11 seems justified." (PMID 39109335, 2024). "This is also the case for 8/14 syndromic HCM (CACNA1C, FLNC, PRKAG2, PTPN11 (Noonan), PTPN11 (Noonan syndrome with multiple lentigines), RAF1, RIT1, TTR), 3/12 DCM (DES, TNNC1 and TNNT2), and 2/6 ARVC (JUP, TMEM43) gene-disease pairs." (PMID 37872640, 2023). "Herein, we report one male patient with multiple pigmented skin spots who was initially diagnosed with multiple acquired melanocytic nevi but was later diagnosed with LEOPARD syndrome (OMIM #151,100) based on a germline PTPN11 mutation." (PMID 34488904, 2021). "LEOPARD syndrome patients most commonly manifest congenital heart defects and cardiac hypertrophy because of mutations in the PTPN11 gene encoding Shp2 that generally result in impaired Shp2 catalytic activity." (PMID 25802336, 2015). "Mutations in PTPN11 are related to the development of human diseases known as NOONAN and LEOPARD syndromes." (PMID 25137153, 2014). "Missense mutations in the PTPN11 gene are associated with the dominantly inherited genetic disorders, Noonan syndrome (NS) (OMIM 163950) and LEOPARD syndrome (LS) (OMIM 151100)." (PMID 24736444, 2014). "We have reported on an individual with LEOPARD syndrome and multiple GCG of the jaw caused by alterations in PTPN11." (PMID 25409853, 2014). "Noonan syndrome with multiple lentigines (NSML), previously known as LEOPARD syndrome, is an autosomal dominant disorder most commonly caused by a mutation in the tyrosine phosphatase non-receptor type 11 gene (PTPN11)." (PMID 38515811, 2022). "In contrast to the previous diagnosis, based on the multiple lentigines confirmed by histological analysis, a genetic study revealing a germline PTPN11 mutation, and ECG analysis suggesting potential cardiac defects, we diagnosed the child with LEOPARD syndrome." (PMID 34488904, 2021). "LEOPARD syndrome (LS) is a rare autosomal dominant inherited or sporadic genetic disorder caused commonly by missense mutations in the protein-tyrosine phosphatase-nonreceptor type 11 (PTPN11) gene." (PMID 37260585, 2023).
LEOPARD syndrome (continued). "Recognition that LEOPARD syndrome mutations, despite their reduced src homology 2 (SH2) phosphatase activity, have gain-of-function developmental defects provided the first satisfying rationale for how PTPN11 mutations with opposite effects on phosphatase activity might produce analogous phenotypes." (PMID 26935104, 2016). "Seven genes (PTPN11, SOS1,KRAS, RAF1, BRAF,SHOC2 and MEK1, alias MAP2K1) have beencausally related to NS and closely related conditions (including LEOPARDsyndrome) and clinically related disorders (e.g. neurofibromatosis type 1)." (PMID 21526175, 2011).
lung carcinoma (67 papers, 2010 to 2026). "The upregulation expression of the PTPN11 gene that encodes SHP2 protein exists in melanoma, liver cancer, and lung cancer." (PMID 31805633, 2019). "PTPN11 positively regulates TGF1-induced EMT in lung cancer, and the PTPN11 E76K mutation that is detected in ALK14 was proven to be an activating mutation in lung cancer cells." (PMID 29300322, 2018). "First of all, mutations that activate PTPN11 can actually be detected in lung cancer." (PMID 38504984, 2024). "In addition, PTPN11 mutations have also been linked to the occurrence of solid tumors (e.g., carcinoma of the lungs, hepatic cell carcinoma, breast, ovarian, gastric, and prostate cancers) and NS." (PMID 38025540, 2023). "However, a low prevalence of somatic PTPN11 mutations has been detected in lung cancer." (PMID 36810562, 2023). "Of note, PTPN11 is not only essential for lung cancer cell growth, but also confers chemotherapy resistance." (PMID 35957898, 2022). "Moreover, PTPN11 confers cisplatin resistance to lung cancer cells through activation of the AKT-CA916798 pathway and the Ras/phosphoinositide 3-kinase (PI3K)/AKT1/survivin pathway, respectively." (PMID 35957898, 2022). "However, we found pathological mutations in the PTPN11, NF1, CUX1, IKZF1 gene and TERT promoter, which better fit a diagnosis of a melanoma than of lung cancer." (PMID 34819052, 2021). "Consequently, PTPN11 inhibitors in combination with chemotherapy may be a promising therapy strategy for patients with lung cancer." (PMID 35957898, 2022). "Studies have found that the combination of the PTPN11 inhibitor SHP099 and MEK inhibition can suppress the proliferation of various cancer cells including lung cancer; similarly, PTPN11 knockout and MEK inhibition have similar effects in vitro." (PMID 36870024, 2023). "We found that high PTPN11 expression levels were obtained in most types of cancer, including HNSC, melanoma, lymphoma, testis cancer, GBM, urothelial cancer, COAD, SKCM, BRCA, OV, lung cancer, CESC, PRAD, endometrial cancer, liver cancer, STAD, and PAAD." (PMID 35802774, 2022). "Almost half (48.4%) of our lung cancer patients had lung squamous cell carcinoma (SCC), which is often perceived to lack molecular targets, however our results suggest that KRAS, PIK3CA, PTPN11 and CDKN2A, in particular, could potentially be actionable targets in lung SCC." (PMID 32087721, 2020).
melanoma (60 papers, 2010 to 2025). A malignant, usually aggressive tumor composed of atypical, neoplastic melanocytes. "Secondly, a molecular diagnosis confirms that these specific patients with PTPN11 mosaic nevus spilus are at risk of melanoma." (PMID 36566878, 2023). "In this study, one older adult developed two primary melanomas within the same nevus spilus, with an increased allele load indicative of the clonal expansion of PTPN11 mosaic melanocytes into melanoma." (PMID 36566878, 2023). "Specifically, nevus spilus can also be caused by variants in HRAS, but HRAS is a rare driver of melanoma and is less frequently found mutated in melanoma than PTPN11." (PMID 36566878, 2023). "Mutations that constitutively activates PTPN11 play oncogenic roles in melanoma by driving anchorage-independent colony formation and tumor growth." (PMID 30934534, 2019). "Although these data are preliminary, this is a tantalizing suggestion that heterozygous deletions of PTPN11 may constitute a previously unreported group of potential driver mutations in melanoma." (PMID 36566878, 2023). "Consequently, SHP2 behaves as a pro-oncogenic protein in many cancer types, and PTPN11 gain-of-function mutations are relatively frequent in human tumors, such as endometrium, hematopoietic/lymphoid, melanoma, and neuroblastoma tumors." (PMID 36755664, 2022). "To approximate SHP2-silenced B16F10 tumors, we selected human melanomas expressing the 10%–50% highest and 10%–50% lowest PTPN11 levels." (PMID 40131370, 2025). "Identification of a mosaic intragenic deletion causing the same phenotype as known driver missense variants has led to the identification of deletions involving PTPN11 in somatic form in a melanoma cohort." (PMID 36566878, 2023). "The finding of deletions involving the whole of PTPN11 in 8 of 346 melanoma samples in this study suggests an interesting new perspective on the role of PTPN11 in driving melanoma." (PMID 36566878, 2023). "Previous studies showed that PTPN11 was commonly active in human melanoma samples and played a carcinogenic role in melanoma by regulating Ras and GSK3β signaling pathways." (PMID 35802774, 2022). "In vitro, exosomes released from B16F0 murine melanoma cells inhibited the proliferation of T cells by delivering PTPN11(SHP-2) mRNA and protein." (PMID 32858889, 2020). "To explore the clinical significance of SHP2 in melanoma, we analyzed PTPN11 mRNA level in the Oncomine database." (PMID 27650545, 2016). "Next three genes in the order of decreasing cross-talk frequency are NRAS (cf = 41), RAF1 (cf = 38) and PTPN11 (cf = 38)- the genes are known for its aberrant behaviour in melanoma." (PMID 26558755, 2015). "Also, we found that PTPN11 expression was significantly higher in metastatic compared with primary melanoma tissues, linking high PTPN11 expression with disease progression." (PMID 40131370, 2025). "Prospective studies with functional analysis of PTPN11 deletions in melanoma will however be needed to establish whether this is correct." (PMID 36566878, 2023). "PTPN11 missense and short insertion‒deletion variants have been reported in 58 of 1,030 (6%) melanoma samples in the COSMIC database (including two of the variants we describe in this study), and PTPN11 has recently been implicated in the pathogenesis of BRAF-wild-type melanoma." (PMID 36566878, 2023). "Therefore, sporadic melanoma is likely to be a better source of tissue for the study of the signaling pathway effects of PTPN11 deletions going forward." (PMID 36566878, 2023). "A. PTPN11 mRNA expression weakly associated with reduced CD274 mRNA expression in melanoma tumors regardless of ICI exposure." (PMID 34437586, 2021). "For example, it has been found that melanoma exosomes containing both protein and mRNA of PTPN11 could be efficiently delivered and dose-dependently increase PTPN11 abundance in T cells." (PMID 34650968, 2021). "PTPN11 mRNA is significantly elevated in metastatic melanoma versus primary melanoma." (PMID 27650545, 2016).
melanoma (continued). "Notably, when compared to the benign melanocytic skin nevus, which is commonly viewed as the precursor of melanoma, PTPN11 mRNA was significantly up-regulated in melanoma." (PMID 27650545, 2016). "Mutations found in melanomas on the dorsal hand and foot were reported to be similar to those in melanomas at other sites of intermittently sun-damaged skin, whereas subungual and interdigital melanomas (n = 13) exhibited diverse mutations in PIK3CA, STK11, EGFR, FGFR3, and PTPN11." (PMID 36983205, 2023). "From the three studies, we hypothesize that the activity of SHP-2, rather than the expression, likely controls the expression of PD-L1 as only a weak relationship between PTPN11 and CD274 expression in either lung adenocarcinomas or melanomas was observed." (PMID 34437586, 2021). "Interestingly, only those derived from the melanoma B16F0 cell line contained both protein and mRNA for protein tyrosine phosphatase non-receptor type 11 (PTPN11) which inhibited T-cell proliferation." (PMID 33435564, 2021). "Higher melanin synthesis rates of human melanoma cells expressing tyrosine-protein phosphatase non-receptor type 11 have been observed in vitro, supporting the link between PTPN11 and hyperpigmentation in NSML patients." (PMID 33396879, 2020).
acute myeloid leukemia (51 papers, 2010 to 2026). Acute myeloid leukemia (AML) is a group of neoplasms arising from precursor cells committed to the myeloid cell-line differentiation. "Mutations in protein tyrosine phosphatase non-receptor type 11 (PTPN11) have been considered late acquired mutations in acute myeloid leukemia (AML) development." (PMID 41729075, 2026). "Although RAS/MAPK pathway mutations affecting NRAS, KRAS, and/or PTPN11 are common in de novo or acute myeloid leukemia (AML)-myelodysplasia-related (MR), BRAF variants rarely occur in AML." (PMID 39596583, 2024). "Acquisition of a PTPN11 mutation was observed in one patient who underwent follow-up NGS testing during progression from chronic myelomonocytic leukemia to acute myeloid leukemia." (PMID 38544839, 2024). "In contrast, pan-hematopoietic cell expression of the E76K mutant led to acute myeloid leukemia as well as T and B cell leukemia indicating that the particular phenotype depends on the Ptpn11 mutation and the site of expression." (PMID 35983034, 2022). "We studied the combined effect of both Ptpn11 gain-of-function mutation (D61Y) and Dnmt3a haploinsufficiency on mouse hematopoiesis, the presence of which has been described in both juvenile myelomonocytic leukemia and acute myeloid leukemia patients." (PMID 29464054, 2018). "The increased activation of RAS signaling in mature but not immature cells may explain why PTPN11 mutations, when acquired as a first hit, lead to differentiating myelomonocytic leukemia rather than acute myeloid leukemia." (PMID 40057493, 2025). "Of note, mutations in several of the genes that confer leukemia predisposition (e.g., CEBPA, ETV6, GATA2, NF1, RUNX1, PTPN11, CBL, and RAS) are also frequently found in sporadic acute myeloid leukemia (AML) or myelodysplastic syndrome (MDS)." (PMID 29326930, 2017). "In addition, PTPN11 mutations have been identified in pediatric acute leukemias, such as myelodysplastic syndrome (MDS) (10%), B cell acute lymphoblastic leukemia (B-ALL) (7%), and acute myeloid leukemia (AML) (4%)." (PMID 21799948, 2011). "We discuss the clinical characteristics and prognostic significance of adult individuals with PTPN11 mutations who have developed acute myeloid leukemia (AML) (none acute promyelocytic leukemia)." (PMID 38025540, 2023). "For acute myeloid leukemia the panel is composed of FLT3ITD/FLT3-TKD, NPM1, C-KIT, PTPN11 and CEBPA." (PMID 23863689, 2013).
hepatocellular carcinoma (50 papers, 2014 to 2025). A malignant tumor that arises from hepatocytes. "SHP2, encoded by PTPN11, has been shown to play tumor-suppressor roles in a number of cancer models such as hepatocellular carcinomas." (PMID 34831413, 2021). "Loss of Shp2 promotes hepatocellular carcinoma (HCC), suggesting that PTPN11 functions as a tumor suppressor in HCC tumorgenesis." (PMID 25198338, 2014). "The correlation of miR-186 and PTPN11 was confirmed in Hepatocellular carcinoma (HCC) patients’ tissues." (PMID 33816273, 2021). "Decreased PTPN11 expression was detected in a subfraction of human hepatocellular carcinoma specimens." (PMID 28750679, 2017). "Accordingly, decreased PTPN11 expression was detected in a subfraction of human hepatocellular carcinoma specimens." (PMID 26768750, 2016). "For instance, in hepatocellular carcinoma (HCC), miR−186 markedly enhanced the apoptosis rate of cisplatin-treated HCC cells by targeting PTPN11 and elevating the expression of apoptosis-related proteins." (PMID 40710326, 2025). "Supporting our findings, PTP4A1 has previously been shown to protect RIG-I from SHP2/PTPN11-dependent degradation, and knock-out of PTP4A1 reduced RIG-I levels and abolished RIG-I-dependent upregulation of IFNB1 in HepG2 hepatocellular carcinoma cells." (PMID 39995872, 2025). "The vast majority of the reported PTPN family members hold an inhibitory role in hepatocellular carcinoma (HCC), with the exception of PTPN11, which drives HCC progression by potentiating oncogenic proteins such as β-Catenin, PIK3CA and MET, and is associated with chemoresistance in HCC patients." (PMID 35957898, 2022). "In hepatocellular carcinoma, miR-186 inhibits self-renewal of hepatocellular carcinoma stem cells and is more sensitive to cisplatin treatment by binding to 3’-UTR of PTPN11 mRNA and reducing its expression." (PMID 35957898, 2022). "In summary, this study reports that oncogenic miR-500a-3p promotes the CSCs properties and tumourigenicity by negatively regulating SOCS2, SOCS4 and PTPN11, leading to activation of the STAT3 signalling pathway in hepatocellular carcinoma." (PMID 28750679, 2017). "Tanshinone IIA may induce hepatoma cell death by downregulating miR-30b transcription and subsequently upregulating PTPN11 levels, which in turn stimulates the SHP2 pathway." (PMID 36300115, 2022). "Collectively, these results indicated that miR-500a-3p promotes CSC-like phenotypes of HCC cell via targeting SOCS2, SOCS4 and PTPN11, which further promotes the progression of hepatocellular carcinoma." (PMID 28750679, 2017). "Recently, PTPN11 (SHP2), a non-receptor type PTP, was reported to play an oncogene-like role in laryngeal cancer, hepatocellular carcinoma and glioblastoma, and the mechanism appeared to involve dephosphorylating RAS to activate the RAS/ERK pathway." (PMID 29915291, 2018).